FGF23 (fibroblast growth factor 23)
Diseases named in the same sentence as FGF23 in open-access papers (continued):
Sharing a sentence is not in itself a finding about the gene and the disease.
hyperphosphatemia (continued). "Further, we found that G-3-P dehydrogenase 1 (Gpd1), a cytosolic enzyme that synthesizes G-3-P and oxidizes NADH to NAD+, is required for phosphate-stimulated G-3-P and FGF23 production and prevention of hyperphosphatemia." (PMID 36821389, 2023). "Therefore, it seems that probably an indirect lowering of FGF23 levels through correction of iron deficiency, anemia, and hyperphosphatemia by iron-based phosphate binders and induction of more physiological EPO production might have a better effect than direct blocking of FGF23 signaling." (PMID 36831276, 2023). "Prolonged increases in extracellular fluid phosphate levels stimulate FGF23 production, which subsequently reduces renal phosphate reabsorption, effectively counteracting hyperphosphatemia." (PMID 37635983, 2023). "As FGF-23 levels start rising early in CKD as compensation to prevent hyperphosphatemia, these high values of FGF-23 were consistent with other studies." (PMID 36812096, 2023). "Fibroblast growth factor 23 (FGF23) is a bone-derived hormone that plays a key role in phosphate homeostasis, primarily in response to hyperphosphatemia." (PMID 36829583, 2023). "Several studies showed that the global deletion of Fgf23 in Hyp mice, resulting in hyperphosphatemia, hypervitaminosis D, and early mortality, reverted the phenotype of Hyp mice to a bone phenotype resembling that of Fgf23-null mice." (PMID 37943605, 2023). "Hyperphosphatemia, hyperparathyroidism, high levels of fibroblast growth factor-23 (FGF-23), low levels of 1,25-dihydroxyvitamin D (calcitriol), and hypocalcemia characterize patients with advanced CKD and ESRD." (PMID 36766888, 2023). "Hyperphosphatemia, the fluctuations of calcium such as hyper and hypocalcemia, hyperparathyroidism, the reduction of alpha Klotho, and the increase in FGF-23 are the main determinants of AS in CKD." (PMID 37510208, 2023). "Our findings further support that high levels of FGF-23 in serum in HD patients with normal or low serum phosphate concentration cannot be attributed to hyperphosphatemia." (PMID 36812096, 2023). "Hyperphosphatemia stimulates fibroblast growth factor 23 (FGF-23), a protein that is secreted by bones." (PMID 36815007, 2023). "Unlike other studies, our experimental approach allowed assessing a bone response to CKD before the development of hyperphosphatemia and systemic elevation of conventional phosphate regulatory factors, FGF23 and PTH." (PMID 37108433, 2023). "As CKD progresses, several biochemical changes occur, including hyperphosphatemia, hypocalcemia, increased fibroblast growth factor 23 (FGF-23) and PTH levels, as well as vitamin D concentrations." (PMID 37122165, 2023). "By increasing 1,25-vitamin D and calcium levels, SIK inhibition would likely restore normal FGF23 secretion and, thus, correct hyperphosphatemia, as seen in patients with hypoparathyroidism who are treated with calcitriol or calcium." (PMID 37115697, 2023). "First, FGF-23 increases the phosphorus excretion from the kidneys; later on, it further enhances hyperphosphatemia by retention of phosphorus from the kidneys." (PMID 36815007, 2023). "When these individuals are treated with hemodialysis for ESRD, their serum FGF-23 levels rise more noticeably than anticipated given their hyperphosphatemia level." (PMID 36812096, 2023). "High phosphate loading had a negative correlation with cancellous and cortical bone in nephrectomized BKO mice, probably as a result of high circulating FGF23, hyperphosphatemia, and hyperparathyroidism." (PMID 35622784, 2022). "Given the key role of FGF23 to protect the organism against hyperphosphatemia, it can be expected that phosphate increases FGF23 concentrations." (PMID 35629904, 2022). "Although hyperphosphatemia increases fibroblast growth factor 23 (FGF23, a hormone that inhibits the action of NaP2a and NaP2c, decreasing renal tubular resorption of phosphorus), this increase is not enough to compensate for the lack of PTH." (PMID 36382754, 2022).
hyperphosphatemia (continued). "Hyperphosphatemia changes the amount of Klotho, FGF23, PTH, and calcitriol in the body, therefore increasing CVD incidence." (PMID 35928251, 2022). "Our findings demonstrated that the increased femoral bone loss was accompanied by high serum FGF23, PTH, hyperphosphatemia, and hypercalcemia in nephrectomized BKO mice drinking PBS." (PMID 35622784, 2022). "FGF23 increases early in CKD to prevent hyperphosphatemia, which in turn enhances renal phosphate excretion and represses renal phosphate reabsorption." (PMID 35622784, 2022). "The loss of FGF23 ability to regulate phosphate levels through its phosphaturic effect and inhibit PTH secretion was shown in ESRD patients, resulting in hyperphosphatemia and increasing FGF23 levels." (PMID 35269640, 2022). "Both hyperphosphatemia and increased blood calcitriol (active vitamin D) concentrations stimulate FGF‐23 production, which promotes urinary phosphorus excretion and decreases intestinal phosphorus reabsorption." (PMID 35218249, 2022). "Both acute and chronic kidney injury increase circulating FGF23 levels as mechanism to prevent hyperphosphatemia." (PMID 36246903, 2022). "The mice presented with hyperphosphatemia, hyperparathyroidism, and elevated levels of FGF23 and bone turnover markers." (PMID 35900032, 2022). "With a progressive worsening of renal function, hyperphosphatemia, and low levels of vitamin D favor hyperparathyroidism, which appears to occur after FGF-23 levels increase to maladaptive concentrations in patients with ESKD." (PMID 36293076, 2022). "As a result, in patients with CKD, high levels of FGF-23 attenuate hyperphosphatemia, decrease levels of active vitamin D, and inhibit PTH synthesis and secretion." (PMID 36293076, 2022). "FGF23, a phosphaturic hormone, is induced by hyperphosphatemia, and plays a crucial role in bone mineralization." (PMID 35622784, 2022). "The phosphaturic effect associated with the decreased level of 1,25(OH)2D3 is a mechanism of FGF23 to control hyperphosphatemia." (PMID 35806367, 2022). "An imbalance of systemic mineral homeostasis in the elderly particularly impaired renal function, hyperphosphatemia, and additionally led to an increase in FGF23 secretion, resulting in a progressive decrease in bone mineralization." (PMID 35269640, 2022). "The pathophysiological role of FGF23 is not limited to diseases with hypophosphatemia or hyperphosphatemia." (PMID 35084563, 2022). "Of note, phosphate metabolism itself is dysregulated during AKI, and hyperphosphatemia can be present as a result of reduced kidney excretion together with increased fibroblast growth factor 23 (FGF-23) levels." (PMID 35269781, 2022). "Considering the marked hypoferremia and hyperphosphatemia observed in the conditional‐null mice, although the Dmp1‐Cre is known to efficiently recombine the flox‐Fgf23 allele, the sum of both of these systemic Fgf23 drivers may override the suppressive abilities of the targeted deletion." (PMID 35656701, 2022). "Synthesis of 1-α-hydroxylase is induced by hypocalcemia and PTH, whereas 24-hydroxylase activity is potentiated by hyperphosphatemia and FGF-23." (PMID 36293076, 2022). "Nonetheless, other studies in CKD animal models indicated that FGF23 neutralization exacerbates hyperphosphatemia and elevated serum calcitriol, resulting in an increased arterial calcification." (PMID 35269640, 2022). "Meanwhile, FGF23 is a phosphaturic hormone produced by osteocytes and osteoblasts in response to hyperphosphatemia." (PMID 35903313, 2022). "Similar to CKD patients, the adenine group also developed significant hyperphosphatemia, secondary hyperparathyroidism, and severely elevated FGF23." (PMID 35813388, 2022). "FGF23 functions as a regulating phosphate and synthesizes vitamin D. Studies have reported that hyperphosphatemia significantly increases FGF23 expression in patients with CKD." (PMID 35656113, 2022).
hyperphosphatemia (continued). "Previous studies reported that active VD induces expression of the FGF23 and α-klotho genes to attenuate the pro-aging effects of hyperphosphatemia and maintain the plethora of anti-aging and pro-survival actions of renal and circulating klotho." (PMID 35846303, 2022). "In CKD and ESRD patients, increased FGF23 induced by hyperphosphatemia inhibits vitamin D activation and subsequently decreases calcium absorption in the intestine." (PMID 35269640, 2022). "A high Pi load induces expression and secretion of the phosphaturic hormones parathyroid hormone (PTH) and fibroblast growth factor 23 (FGF23) that enhance urinary Pi excretion and prevent the onset of hyperphosphatemia." (PMID 35428804, 2022). "In renal tubules, PTH and FGF‐23 down‐regulate the Na2+‐dependent Pi cotransporters, (NaPi)‐IIa and NaPi‐IIc, and increase urinary Pi excretion to prevent hyperphosphatemia." (PMID 35385223, 2022). "We believe that INHD persistently conveyed a protective effect on survival through modifying the CKD–MBD parameters, such as hyperphosphatemia, representing an FGF23 independent mechanism involved." (PMID 35801203, 2022). "Deletion of Klotho in mice results in a phenotype that resembles CKD, including hyperphosphatemia, elevated FGF23, ectopic soft tissue calcifications, and decreased plasma and renal Klotho." (PMID 35813388, 2022). "Hyperphosphatemia and elevations of fibroblast growth factor 23 (FGF23) are common findings in CKD, with relevant pathophysiological roles regarding diverse CKD complications, including anemia." (PMID 36432528, 2022). "Hyperphosphatemia, vascular calcification, and elevated FGF23 concentrations are the components of CKD-MBD, which exacerbate cardiovascular disease, accounting for around 60% of deaths among patients with CKD on dialysis." (PMID 35928251, 2022). "Three hormones, 1,25(OH)2D3, PTH, and FGF23 negatively regulate phosphate homeostasis and delays the occurrence of hyperphosphatemia." (PMID 35622784, 2022). "As hyperphosphatemia is a major trigger of enhanced FGF23 secretion, high FGF23 plasma levels are typical of CKD." (PMID 35084563, 2022). "FGF23 gene deletion from mice resulted in hyperphosphatemia, thus solidifying the role of FGF23 in reducing serum phosphate levels." (PMID 35928251, 2022). "It seems to prevent the development of hyperphosphatemia—at least in part—by enhancing urinary phosphate excretion via FGF23." (PMID 36084108, 2022). "The main biochemical manifestations of HFTC include hyperphosphatemia, normal serum calcium concentration, high or inappropriately normal 1,25-dihydroxyvitamin D concentration, and in most cases decreased FGF23 concentration." (PMID 36213261, 2022). "Plasma levels of FGF-23 and PTH were higher in the groups fed with high Pi than in those fed with low Pi, as expected based on the hyperphosphatemia associated with dietary Pi overload." (PMID 36074191, 2022). "In conditions of hyperphosphataemia, FGF23 produced by osteoblasts and osteocytes in response to PTH increases renal phosphate excretion by down-regulating the expression of NaPi-IIa and NaPiIIc cotransporters in the proximal tubules." (PMID 36260560, 2022). "Hyperphosphatemia, shedding of proximal tubule cells, and increased levels of fibroblast growth factor 23 (FGF23) lower the expression level of 1α-hydroxylase, which converts 25-hydroxyvitamin D into calcitriol." (PMID 34787531, 2021). "The univariate Cox regression analysis showed that FGF‐23 >528 pg/mL, UN >29.2 mg/dL, and CKD stages 3‐4 were significantly associated with risk for development of hyperphosphatemia (P < .001, P = .003, and P = .01, respectively)." (PMID 34418162, 2021). "Fgf23−/− mice develop hyperphosphatemia as early as 10 days after birth due to increased renal tubular reabsorption of phosphate by NaPi-IIa16." (PMID 33731726, 2021). "An impaired ability to handle dietary P load in renal disease causes hyperphosphatemia and the constant stimulation of PTH and FGF23 secretion." (PMID 33606750, 2021).
hyperphosphatemia (continued). "Both hyperphosphatemia and excessive FGF23 can promote the development of hypertension, vascular calcification, and left ventricular hypertrophy." (PMID 33460402, 2021). "An additional effect of hyperphosphatemia is the inhibition of 1,25(OH)2D3 synthesis, either directly, or indirectly by increasing plasma FGF23 concentration." (PMID 34371838, 2021). "In the future, the therapeutic strategies of hyperphosphatemia need to take FGF-23 as an important target besides direct dephosphorization." (PMID 33748139, 2021). "FGF23-null (FGF23−/−) mice were shown to develop hyperphosphatemia and high serum 1,25(OH)2D3, as well as premature aging features identical to Klotho-knockout (KL−/−) mice." (PMID 36188832, 2021). "Because extracellular phosphate stimulates FGF23 secretion from bone in vivo, it was previously believed that hyperphosphatemia triggers the augmented skeletal FGF23 secretion in CKD as part of an adaptive physiological response." (PMID 33995120, 2021). "In CKD, serum FGF23 levels are elevated due to hyperphosphatemia, and dietary phosphate restriction and phosphate binders are being used to keep FGF23 levels under control." (PMID 33716961, 2021). "Our findings showed that a high-phosphate diet was associated with hyperphosphatemia, despite the increase in PTH, FGF-23 and, consequently, of the fractional excretion of phosphate." (PMID 34357974, 2021). "At advanced stages of CKD, the synthesis of αklotho declines, reducing the binding capacity of FGFR and thus increasing the circulating FGF23 while hyperphosphatemia remains." (PMID 33606750, 2021). "FGF23 secreted in response to hyperphosphatemia binds to FGF23R/Klotho receptors in the parathyroid and the PCT." (PMID 35299844, 2021). "Incidentally, as the pivotal roles of FGF23 and αKlotho in phosphate metabolism have been unveiled, how phosphate metabolism and hyperphosphatemia are involved in CKD-MBD and how they can be clinically treated have become of great interest." (PMID 34069053, 2021). "In hyperphosphataemia, it is classically known that FGF-23 release is mainly coordinated by bone tissue in the blood." (PMID 34360534, 2021). "In contrast, there is evidence that direct targeting of phosphate and FGF receptors can prevent toxicity of FGF23 and hyperphosphatemia in CKD patients." (PMID 33460402, 2021). "PTH acts on bone, kidney and intestine, and is produced in response to hypocalcemia and hyperphosphatemia, as well as low 1,25(OH)2D3 and FGF23." (PMID 34360805, 2021). "On the other hand, in patients with renal dysfunction, the dysregulation of the αKlotho-FGF-receptor prevents the signaling of the P diuretic factor FGF23, resulting in hyperphosphatemia and vascular calcification." (PMID 34445034, 2021). "It is believed that elevated levels of FGF23 can compensate for the hyperphosphatemia or phosphate overload in these diseases." (PMID 34055103, 2021). "It was previously thought that the rise in circulating FGF23 is driven by hyperphosphatemia due to the diminished capacity of the kidneys to excrete phosphate." (PMID 34950827, 2021). "FGF23 null mice exhibited severe hypercalcemia, hyperphosphatemia and hypervitaminosis D, leading to demineralization of the cochlea." (PMID 34721981, 2021). "This makes it unlikely that cFGF23 would have a role in FGF23 inhibition in healthy individuals, as they would be expected to present with hyperphosphatemia." (PMID 33716961, 2021). "We showed that wild type mice on low phosphate diet and Fgf23−/− mice with hyperphosphatemia have increased renal Dnase1 mRNA expression while in Hyp mice with FGF23 excess and hypophosphatemia, Dnase1 mRNA expression is decreased." (PMID 33731726, 2021). "Increased FGF-23 levels and pro-inflammatory cytokines were found in patients with hyperphosphatemia." (PMID 33748139, 2021).
hyperphosphatemia (continued). "1,25(OH)2D/VDR–RXR acts in kidney to induce Klotho (a phosphaturic coreceptor for FGF23) to correct hyperphosphatemia, NPT2a/c to correct hypophosphatemia, and TRPV5 and CaBP28k to enhance calcium reabsorption." (PMID 33553988, 2021). "Administration of cKl to α-klotho null mice, resulted in upregulation of Fgf23 and the prevention of hyperphosphatemia and vascular calcification." (PMID 33716961, 2021). "Hyperphosphatemia also increases the concentration of circulating fibroblast growth factor 23, reduces the synthesis of active vitamin D, and produces hypocalcemia, thereby resulting in secondary hyperparathyroidism." (PMID 34574376, 2021). "Results from mice models are contradicting: Galnt3−/− mice have hyperphosphatemia and increased FGF23 expression, although secretion of intact FGF23 is impaired, but show no sign of abnormal calcification." (PMID 32210002, 2020). "Of note, hypercalcemia, hyperphosphatemia, high PTH, low vitamin levels, and high FGF23 have been per se associated with death, as well as CV events, in several studies in ESKD patients." (PMID 32718053, 2020). "By using immunohistochemistry analysis, investigators showed that partial deletion of Klotho in distal tubule resulted in hyperphosphatemia with elevated plasma FGF23 and increased Npt2a protein expression in the proximal tubule apical membrane." (PMID 32982979, 2020). "FGF23 and Klotho mainly maintain urinary phosphorus excretion; any depleted activity of these molecules leads not only to hyperphosphatemia, but also to premature aging." (PMID 32438707, 2020). "Plasma FGF‐23 levels in GlatmTg(CAG‐A4GALT) mice increased in response to hyperphosphatemia due to secondary hyperparathyroidism by 20 weeks of age." (PMID 32617522, 2020). "With regard to CKD progression, several hormonal and biochemical changes such as hyperphosphatemia, hypocalcemia, increased fibroblast growth factor 23 (FGF-23), and PTH levels as well as vitamin D concentration abnormalities have been suggested." (PMID 33193760, 2020). "Since hyperphosphatemia and high levels of FGF23 were both detected in kl/kl, CKD, and HPD-fed mice, we then explored the effect of FGF23 on HP-mediated changes." (PMID 32938919, 2020). "Hyperphosphataemia appears to be related to the alteration of vitamin D and phosphorus metabolism mediated via fibroblast growth factor 23 (FGF23)." (PMID 32722188, 2020). "As expected, this mouse developed hyperphosphatemia with decreased circulating intact FGF23, despite elevated Fgf23 expression in the bone." (PMID 32457699, 2020). "Phosphate retention, progressive hyperphosphatemia, rising FGF23 levels and low Klotho expression are all observed in patients with progressive CKD and are associated with age-associated CVD." (PMID 32982966, 2020). "In mice, for example, both fibroblast growth factor 23 (FGF23) and the renal transmembrane protein Klotho act as Pi-regulating hormones whose genetic ablation leads to hyperphosphatemia and premature aging phenotypes, including muscle atrophy." (PMID 33136552, 2020). "The delayed onset of hyperphosphatemia is probably due to the anti-regulatory effects of FGF-23 and PTH." (PMID 32823917, 2020). "In order to prevent hyperphosphatemia, the body reacts via the activation of compensatory mechanisms, including an increase in FGF23 and PTH secretion." (PMID 32570781, 2020). "In these patients, hyperphosphataemia arises from a reduction in renal phosphorus clearance, resulting in an increase of fibroblast growth factor-23 (an important factor controlling phosphate metabolism), vitamin D deficiency or resistance and hypocalcaemia." (PMID 31797261, 2020). "FGF23: Hyperphosphatemia often succeeds CKD, hypoparathyreoidism and vitamin D intoxication, but can also result from rare genetic disorders like hyperphosphatemic tumoral familial calcinosis (hFTC)." (PMID 32210002, 2020).